IGFBP7 (insulin like growth factor binding protein 7)
Diseases named in the same sentence as IGFBP7 in open-access papers (continued):
Sharing a sentence is not in itself a finding about the gene and the disease.
cancer (continued). "Despite this, they retained strong expression of core stromal markers such as DCN, VIM, LUM, and IGFBP7, which were consistently observed across both ex vivo and in situ fibroblasts compared to the epithelial cancer cells." (PMID 41198614, 2025). "ADAR2 can edit the mRNA of insulin-like growth factor binding protein 7 (IGFBP7) and change the protease recognition site of matriptase to stabilize IGFBP7 protein, thus stimulating the apoptosis of cancer cells." (PMID 40483535, 2025). "The third target, Insulin-like growth factor-binding protein 7, IGFBP7, is a secreted protein implicated in a variety of cancers." (PMID 39960760, 2025). "Our pancancer analysis also revealed the complicated regulation of IGFBP7 in different cancer types." (PMID 39351597, 2024). "In breast, gastric, prostate, colorectal, and glioma cancers, some studies have reported upregulation of IGFBP7 expression, while others have reported downregulation, indicating a dual role of IGFBP7 in cancer cell proliferation, progression, and prognosis." (PMID 39081862, 2024). "The results revealed that IGFBP7 correlated with several vital cancer‐related biological processes, including collagen fibril organization, extracellular matrix assembly, cell cycle DNA replication and DNA replication initiation." (PMID 39351597, 2024). "Within the tumorigenesis context, accumulating studies clarified that IGFBP7 is upregulated in some types of cancers, while downregulated in others." (PMID 39045455, 2024). "STMGraph categorized healthy regions into 8, 11, and 19, with IGFBP7 showing high expression in healthy region 8 located far from cancer cells." (PMID 39764614, 2024). "We found that the functions of CD93 in different cancers are mainly related to Insulin like growth factor binding protein 7 Gene (IGFBP7)/CD93 pathway via STRING, GeneMania and functional enrichment analyses." (PMID 37483608, 2023). "Research findings demonstrate that IGFBP7 exhibits dual effects, i.e., both anti-cancer and pro-cancer in different types of tumors." (PMID 37568781, 2023). "Our study had some limitations, including that our study excluded patients with cancer and/or cardiac diseases, despite the fact that IGFBP7 expression was observed to be similarly e altered in these patients." (PMID 37174963, 2023). "In order to further explore the expression of IGFBP7 in other cancers, we conducted a pan-cancers analysis using the TCGA and GTEx database." (PMID 37304887, 2023). "In summary, it seems that IGFBP7 is related to two main characteristics of giant cetaceans: increase in body size and suppression of cancer." (PMID 36658131, 2023). "The results indicated that the expression of IGFBPs, especially IGFBP4 and IGFBP7, was significantly correlated with the suppression or activation of a variety of cancer pathways." (PMID 37088808, 2023). "And for the majority of the cancers, IGFBP3, IGFBP4, IGFBP5, IGFBP6 and IGFBP7 were significantly positively associated with stromal, immune as well as ESTIMATE scores including COAD, PCPG, PRAD, READ and STAD." (PMID 37088808, 2023). "The results demonstrated that IGFBP7 was positively correlated with a majority of immunomodulators in the majority of cancers." (PMID 35812369, 2022). "In this study, IGFBP7 was highly correlated with the modulation of the TME in most cancers by pan-cancer analysis." (PMID 35812369, 2022). "Overall, high expression of IGFBP7 increased TIICs, but the activities of the recognition of cancer cells by T cells and killing of cancer cells were decreased." (PMID 35812369, 2022). "Among them, seven genes (FHL1, SELL, VIM, IGFBP7, TNFAIP3, LCP2, and SLC7AB) were associated with the cancer-immunity cycle." (PMID 35565437, 2022). "The expression of IGFBP7 and pan-cancer T cell inflamed score were both significantly positively correlated with the risk score." (PMID 35812369, 2022).
cancer (continued). "In this study, pan-cancer analysis indicated that IGFBP7 was positively correlated with immunomodulators, the infiltration levels of TIICs, and immune checkpoints in the majority of cancers." (PMID 35812369, 2022). "Overall, these findings indicated that IGFBP7 played a key role in regulating microenvironment immunity across most cancers." (PMID 35812369, 2022). "It has been suggested that IGFBP7 acts primarily as a tumor suppressor, since its expression is reduced in neoplastic tissues of various types of cancer, including liver tumors." (PMID 34440203, 2021). "Another limitation is our study excluded patients with cancer and/or cardiac diseases, whereas IGFBP7 expression was also found to be changed in these patients." (PMID 34489947, 2021). "IGFBP7 is a secreted factor that suppresses cancer cells protein synthesis, growth and survival by competing with IGF1 binding to the IGF1R, thereby preventing its activation." (PMID 33673232, 2021). "Increasing evidence has reported that IGFBP7 expression is regulated by epigenetic changes, especially by DNA methylation in various cancers 16, 30-33." (PMID 33531979, 2021). "To determine the expression levels of IGFBP7 in different cancers, we analyzed IGFBP7 expression among various cancers using the TIMER database." (PMID 33531979, 2021). "This putative functional homolog of mammalian insulin-like growth factor-binding protein 7 (IGFBP7) is known to be released from experimentally induced cancer cells in adult flies." (PMID 33659253, 2021). "The objective of this review is to present a comprehensive overview of the relationship between IGFBP7 and cancer, as well as highlighting IGFBP3 crosstalk with IGFBP7 reported in recent studies." (PMID 32500027, 2020). "In different types of cancers, IGFBP7 plays an inhibitory role by curbing proliferation and inducing apoptosis and senescence." (PMID 32500027, 2020). "In the last few years, there has been an increasing number of studies and findings regarding the roles and mechanisms of IGFBP3 and IGFBP7, and their relationships with many kinds of diseases, especially in different cancer types." (PMID 32500027, 2020). "When present, IGFBP7 expression had a strong intensity and was restricted to clusters of cancer cells (6/11 samples)." (PMID 33019700, 2020). "IGFBP7 mRNA expression in cancer cells isolated from malignant pleural effusions after acquired resistance to EGFR-TKI was significantly higher than in cancer cells from treatment-naïve effusions." (PMID 30609749, 2019). "Of the 82 unique prognostic biomarkers identified, meta-analyses showed prominent biomarkers, including COX-2, PAK-1, p14ARF, PD-L1, MET, LC3B, IGFBP7 and LGR5, associated to each hallmark of cancer." (PMID 30185893, 2018). "IGFBP7, a member of the insulin like growth factor receptor family, was identified as most promising prognostic biomarker in this hallmarks of cancer feature." (PMID 30185893, 2018). "The expression of IGFBP-7 is diminished in various types of human cancer cell lines, including prostate, breast, colon, and lung cancer." (PMID 25880247, 2015). "Aberrant insulin-like growth factor-binding protein 7 (IGFBP-7) expression has been found in various cancers such as prostate, breast, and colon." (PMID 25880247, 2015). "Although our and a few other studies have shown elevated expression of AGM/IGFBP-rP1/IGFBP7 in the vasculature of some types of cancer tissues 15,16,21,39, others have reported opposite results 22–24." (PMID 24737780, 2014). "Both up-regulated expression and down-regulated expression of IGFBP7 is observed in different types of cancer." (PMID 20158915, 2010). "Furthermore, the function of CD93 in different cancers was primarily related to the IGFBP7/CD93 signaling pathway." (PMID 40943530, 2025). "IGFBP7 is a secreted protein that has been extensively studied in the context of cancer biology." (PMID 39788916, 2025).
cancer (continued). "Additionally, GSEA revealed that IGFBP7 was related to several cancer‐related pathways, including cell adhesion molecule, extracellular matrix receptor interaction, cell cycle, DNA replication and base excision repair pathways." (PMID 39351597, 2024). "The role of IGFBP7 in cancer has been a highly researched area of interest." (PMID 39081862, 2024). "We evaluated urine NGAL, KIM-1, TIMP-2, and IGFBP-7, collected during cisplatin infusions early in cancer therapy (early visit [EV]) and later in cancer therapy (late visit [LV]), for predicting signs of CKD and HTN at 3 months after cisplatin therapy completion." (PMID 38668904, 2024). "These entirely different manifestations suggest that IGFBP7 may function as a “double-edged sword” in cancer cell growth and progression, displaying an ambiguous action in distinct types of cancers." (PMID 39045455, 2024). "The diverse functions exhibited by IGFBP7 in different types of cancer can indeed be confusing." (PMID 37568781, 2023). "In addition, IGFBP2 and IGFBP7 showed different prognostic roles in multiple cancer types, we therefore created forest plots to show specific predictive effects in various types of cancer." (PMID 37088808, 2023). "However, IGFBP7 acts as a cancer-promoting gene in esophageal adenocarcinoma and neck squamous cell carcinomas." (PMID 35812369, 2022). "In terms of chemotherapy drug response, the lower expression of IGFBP7 could make the cancer cells more sensitive to most chemotherapy drugs but resistant to cisplatin." (PMID 35812369, 2022). "The results of the correlation between IGFBP7 gene expression and the T-cell inflamed ssGSEA score indicated that IGFBP7 expression was significantly positively related to the pan-cancer T cell inflamed score in the training cohort and validation cohorts (IMvigor210 cohort and GSE176307)." (PMID 35812369, 2022). "The expression level of IGFBP7 is regulated by DNA methylation in various cancer types 14-17." (PMID 33531979, 2021). "The results revealed that the expression levels of IGFBP7 were divergent in different cancers." (PMID 33531979, 2021). "Since the IGF axis could contribute to cancer progression and invasion, it is now widely accepted that aberrant methylation of IGFBP7, IGFBP-4, IGFBP-3, IGF-1R, IGF-1, and IGF-II promoters could be a potential factor in various common human cancers." (PMID 33768092, 2021). "These entirely different opinions suggest that IGFBP7 functions may be a “double-edged sword” in cancer proliferation, progression, and prognosis." (PMID 32500027, 2020). "The expression of IGFBP3 and IGFBP7 is often reduced in several kinds of cancers." (PMID 32500027, 2020). "We found that 30 of these genes which included Nckap1l, Ncf1, Pla2g15, Unc93b1, Lrrc33, Rgs10, Gmfg, Rbm25, C3ar1, Ccdc88b, Fam105a, Gng11, Phc1, Rasa4, Dag1, Tyrobp, Tmsb4x, Cfp, Prkd1, Gp49a, Trem2, C1qc, Lyz2, Igfbp7, Rab30, Cxcl16, Egfl7, Ube2r2, Pltp, and Cfb, showed a relation with cancer." (PMID 32812032, 2020). "IGFBP7 overexpression is also being evaluated as a potential cancer biomarker." (PMID 30609749, 2019). "In addition, we found significant differences in the DNA methylation levels of IGFBP7 of normal crypts from the region adjacent to the cancer and proximal and distal regions between the left- and right-side colonic mucosa." (PMID 28533824, 2017). "A predicted CpG island overlapping the first exon of IGFBP7 was investigated for methylation analysis as evidence for alteration of methylation status has been demonstrated in the analysis of a variety of other cancer types." (PMID 25886299, 2015). "We investigated genetic and epigenetic mechanisms of inactivation of IGFBP7 expression as independent studies have demonstrated such classical mechanisms may abrogate IGFBP7 function in various cancer types." (PMID 25886299, 2015). "Previously the potential role of IGFBP-7 in cancer invasion has been reported." (PMID 25880247, 2015).
cancer (continued). "In pervious report has suggested the potential role of IGFBP-7 in cancer invasion." (PMID 25880247, 2015). "Establishing and examining the role of IGFBP7 in lifespan may shed light on the relationship between cellular senescence, cancer and whole organism aging in mammals, an important emerging field of study." (PMID 21108726, 2011). "Decreased IGFBP7 expression has been observed in some cancers and leiomyomata." (PMID 19019211, 2008). "However, the role of IGFBP7 appears to exhibit a complex pattern across different types of cancer." (PMID 39081862, 2024). "Additionally, it is possible that the effects of IGFBP7 are context-dependent and may vary according to the stage and type of cancer." (PMID 37568781, 2023). "IGFBP2 and IGFBP7 expression may impact the prognosis of more cancer types." (PMID 37088808, 2023). "Interestingly, the role of IGFBP7 in cancer progression is still controversial." (PMID 37568781, 2023). "Notably, the recognition of cancer cells by T cells (Step 6) was weakened by IGFBP7." (PMID 35812369, 2022). "Accordingly, IGFBP7 and GDF-15, two molecules found to be related with cancer and not only with cardiovascular disease states, in the PREDICTOR cohort were found to predict not only all-cause mortality, but also the probability of cancer death after full adjustments." (PMID 34217226, 2021). "These entirely different manifestations suggest that IGFBP7 functions may be a “double-edged sword” in cancer cell proliferation, progression, and prognosis, displaying an ambiguous action as an oncogene or suppressor gene in distinct types of cancers." (PMID 32500027, 2020). "Additionally, IGFBP7 functions as a tumor suppressor gene in different cancer types." (PMID 33233533, 2020). "Relatively speaking, IGFBP4, IGFBP7 and IGFBPL1 showed more amplifications of copy number in multiple cancer types." (PMID 37088808, 2023). "TFF1, IGFBP7, JUNB, CLDN18 and LINC01133 genes were among the top genes of the primary cancer cells." (PMID 34055623, 2021). "Death rates for cancer in the upper tertile of GDF-15 and IGFBP7 were 11.5% and 9.7%, compared to 3.9% and 6.0% in the lower tertile (p < 0.0001 and p = 0.011, respectively)." (PMID 34217226, 2021). "IGFBP7 confers resistance to EGFR-TKIs and is a potential therapeutic target for treating EGFR-TKI-resistant cancers." (PMID 30609749, 2019). "For all other hallmarks of cancer features promising prognostic biomarkers were identified as well, including COX-2, PAK-1, p14ARF, MET, LC3B, IGFBP7 and LGR5." (PMID 30185893, 2018). "For the MET-, IGFBP7, and LGR5 pathways targeted therapies have already been studied in other cancer types with varying results, however, the potential to target these biomarkers in EAC is yet to be investigated." (PMID 30185893, 2018). "We examined DNA methylation levels of SFRP1, SFRP2, SFRP5, DKK2, DKK3, mir34b/c, RASSF1A, IGFBP7, CDKN2A, and MLH1 in cancerous glands and normal crypts isolated from cancer tissue and the surrounding normal mucosa." (PMID 28533824, 2017). "Insulin-like growth factor-binding protein 7, also known as IGFBP-rP1 and MAC25, can inhibit the proliferation of cancer cells, and its expression is downregulated in certain cancers." (PMID 20407444, 2010). "A similar ambiguity of their role in cancer progression was indicated for THBS1 and IGFBP7." (PMID 39960760, 2025). "IGFBP7 is a secreted protein whose abnormal expression has been found in many types of cancer and which has different clinical values in non-cancerous diseases." (PMID 37568781, 2023). "Meanwhile, we did not observe that the killing of cancer cells was significantly downregulated by IGFBP7 in the TCGA cohort but was found in both the IMvigor 210 and GSE176307 cohorts." (PMID 35812369, 2022). "In addition, IGFBP7 and more so GDF-15 predicted cancer mortality (147 events, 27.9% of all deaths)." (PMID 34217226, 2021).
cancer (continued). "For each organ-specific cancer cohort, we first evaluated relative differences between cases and controls for three spiked-in recombinant proteins—SDF-1β, IGF1, and IGFBP7, each of which served as internal quality control and was spiked in at a ratio case/control respectively of 1:10, 1:1, and 10:1." (PMID 33267867, 2020). "We examined the DNA methylation levels of SFRP1, SFRP2, SFRP5, DKK2, DKK3, mir34b/c, RASSF1A, IGFBP7, CDKN2A, and MLH1 in normal colonic crypts isolated from regions that were adjacent to the cancer, as well as distal and proximal regions (left and right sides)." (PMID 28533824, 2017). "EAC exhibits the enhanced extracellular matrix remodeling (collagens, IGFBP7, PLAU) effects expected in an aggressive form of cancer, as well as evidence of reduced expression of genes associated with mucosal (MUC6, CA2, TFF1) and xenobiotic (AKR1C2, AKR1B10) defenses." (PMID 21829465, 2011). "It is possible that local changes in IGFBP7 are not reflected in IGFBP7 levels in the peripheral blood, at least with regard to cancer." (PMID 19019211, 2008). "There is a lack of studies on the biological functions of IGFBP7 in cancer, especially in GC." (PMID 39351597, 2024). "Although we did not observe that high expression of IGFBP7 could significantly weaken the Step 6, in these two validation cohorts, the killing of cancer cells (Step 7) was downregulated in the IGFBP7 high group." (PMID 35812369, 2022). "Together, IGFBP7 may provide potential value for the immunotherapy of cancer, but the role of IGFBP7 in BLCA has not been elucidated." (PMID 35812369, 2022). "Therefore, as we demonstrate here, high expression of IGFBP7 did not seem to enhance the cancer immunity cycle but tended to diminish." (PMID 35812369, 2022). "However, despite these strong links between IGFBP7 and tumorigenesis, we did not observe a relationship between serum IGFBP7 and three different types of cancer." (PMID 19019211, 2008). "Moreover, IGFBP7 may be able to differentiate not only between individuals with and without cancer but also between early and late disease stages." (PMID 38893148, 2024).
kidney disease (8 papers, 2014 to 2024). "The effect of hypoxia on IGFBPs was previously reported with IGFBP7 in kidney disease." (PMID 34646401, 2021). "The secretion of [IGFBP7] · [TIMP-2] in this patient might have been connected to his renal disease." (PMID 26651477, 2015). "Prior animal studies have examined TIMP-2 in relation to AKI, and several studies have examined IGF binding proteins in renal disease but none have directly determined the performance of [TIMP-2]·[IGFBP7] for the prediction of RIFLE I/F AKI in an experimental model." (PMID 27245788, 2016).
infection (6 papers, 2017 to 2023). The state of being infected such as from the introduction of a foreign agent such as serum, vaccine, antigenic substance or organism. "In addition, it was found that infection with Helicobacter pylori was also associated with high expression levels of IGFBP7 mRNA." (PMID 37568781, 2023). "Although the experimental data connecting the adoption of aerobic glycolysis by KCs to the production of IGFBP7 are missing, we suggest that this mechanism may be relevant for the mobilization of nutrients for immune cells, upon infection." (PMID 33659253, 2021). "Analysis of the vessel data revealed several proteins related to the acute-phase response to infection (Hp, Hpx, Serpina3n, Fga/b, Igfbp7, Cfh, and C4b), antigen presentation (Tap1, Tap2, Tapbp, H2-D1, and H2-Q10), and interferon response (Igtp, Gbp2, Irgm1, and Iigp1)." (PMID 32843537, 2020).
kidney (6 papers, 2017 to 2026). "In summary, IGFBP7 serves as a promising biomarker for acute kidney injury, aiding in early detection and prognosis assessment." (PMID 39081862, 2024).